RNU6-1251P (RNA, U6 small nuclear 1251, pseudogene)
Gene: Small nuclear RNA gene on chromosome 20 (43,473,013 to 43,473,119, forward strand). Ensembl gene ENSG00000201372.
Homologues: Orthologues: chimpanzee U6 (100% identical), pig U6 (87% identical), macaque U6 (85% identical). Paralogues in human: RNU6-16P (93% identical), RNU6-33P (93% identical), RNU6-1 (93% identical), RNU6-116P (93% identical), RNU6-11P (93% identical), RNU6-15P (93% identical), RNU6-2 (93% identical), RNU6-37P (93% identical), RNU6-39P (93% identical), RNU6-3P (93% identical), RNU6-4P (93% identical), RNU6-5P (93% identical), and 1288 more.